ALKBH5 (alkB homolog 5, RNA demethylase)
Diseases named in the same sentence as ALKBH5 in open-access papers (continued):
Sharing a sentence is not in itself a finding about the gene and the disease.
gastric cancer (77 papers, 2019 to 2025). A primary or metastatic malignant neoplasm involving the stomach. "In gastric cancer, ALKBH5 is expressed at a low level and is strongly associated with clinical tumor distal metastasis and lymph node metastasis, while the silencing of ALKBH5 promotes tumor invasion and metastasis." (PMID 37063421, 2023). "Meanwhile, a higher expression of ALKBH5 was also positively correlated with a favourable prognosis in gastric cancer; however, it was associated with worse clinical outcomes in colorectal cancer and NSCLC." (PMID 34802443, 2021). "For example, in gastric cancer (GC), silencing of ALKBH5 enhances tumor invasion and metastasis, whereas low ALKBH5 expression is associated with distant metastases and lymph node involvement in clinical settings." (PMID 40271153, 2025). "The RNA demethylase AlkB homolog 5 (ALKBH5), which is highly expressed in gastric cancer, can downregulate CHAC1 by removing m6A modifications." (PMID 40227215, 2025). "Interfering with ALKBH5 expression in gastric cancer cells facilitated metastasis by upregulating Protein kinase, membrane-associated tyrosine/threonine 1(PKMYT1)." (PMID 39791162, 2025). "For example, ALKBH5 is downregulated in gastric cancer and inhibits gastric cancer metastasis by inhibiting WRAP53 translation in a m6A-dependent manner." (PMID 40774945, 2025). "The diminished expression of ALKBH5 in gastric cancer is correlated with increased tumor metastasis and lymph node involvement." (PMID 39791162, 2025). "ALKBH5 plays a context-dependent role in gastric cancer, reported as either upregulated or downregulated across studies." (PMID 41228380, 2025). "For instance, the m6A modification of PKMYT1 by ALKBH5, a demethylase in gastric cancer was demonstrated to suppress cell invasion." (PMID 40069867, 2025). "In gastric cancer, the RNA demethylase ALKBH5 (Alkylated DNA repair protein alkB homolog 5) removes an m6A modification from CHAC1 mRNA, a mark normally associated with transcript stability." (PMID 41488051, 2025). "The dynamic regulation of m6A modifications by demethylases FTO and ALKBH5 under hypoxia plays a critical role in the adaptation of gastric cancer cells to oxygen-limited environments." (PMID 39824841, 2025). "In gastric cancer, high ALKBH5 expression correlates with aggressive clinical features and poor prognosis." (PMID 39192357, 2024). "The m6A eraser ALKBH5 promotes the invasion and metastasis of gastric cancer (GC) by removing the m6A modification on the lncRNA NEAT1." (PMID 38895621, 2024). "Targeting IGF2BP3 in gastric cancer HGC-27 cells resulted in a significant downregulation of PKMYT1 expression, highlighting the potential role of the ALKBH5/PKMYT1/IGF2BP3 regulatory signaling pathway in gastric cancer metastasis." (PMID 38856795, 2024). "They showed that ALKBH5 is significantly expressed in gastric cancer samples enhancing gastric cell proliferation and metastasis." (PMID 39136000, 2024). "Here we show a different mechanism in gastric cancer: CD58 is negatively posttranscriptionally regulated by HSPA4/ALKBH5 via m6A demethylation." (PMID 38589927, 2024). "We discovered that the two demethylases (ALKBH5 and FTO) showed a little mutation in gastric cancer samples whilst the highest mutation frequency was exhibited by ZC3H13, followed by VIRMA." (PMID 38206646, 2024). "Both ex vivo and in vivo studies confirmed ALKBH5’s role in promoting gastric cancer cell proliferation and metastasis." (PMID 39192357, 2024). "Studies have revealed that the downregulation of the demethylase ALKBH5 leads to increased expression of PKMYT1 in gastric cancer." (PMID 38570712, 2024). "Demethylase ALKBH5 inhibited the metastatic ability of gastric cancer cells through negative regulation of the expression of protein kinase, membrane-associated tyrosine/threonine 1 (PKMYT1), a member of the serine/threonine protein kinase family." (PMID 38856795, 2024).
gastric cancer (continued). "We further uncover the molecular mechanism by which HSPA4/ALKBH5/CD58 axis upregulates PDL1 expression in gastric cancer cells and inhibits the cytotoxicity of CD8+ T cells in tumor environment." (PMID 38589927, 2024). "Taken together, these findings suggest that ALKBH5 is upregulated in gastric cancer and indicates a worse prognosis for patients with GC." (PMID 38007439, 2023). "Mice injected with MGC-803 control cells developed gastric cancer similar to that observed in humans, whereas overexpression of ALKBH5 significantly enhanced tumor formation." (PMID 38007439, 2023). "We then investigated ALKBH5 expression in both normal and gastric cancer tissues from our clinical center using RT-qPCR, western blotting, and immunohistochemical (IHC) analyses." (PMID 38007439, 2023). "Further detection results demonstrated that both LncRNA NEAT1 and ALKBH5 were overexpressed in gastric cancer cells and tissues." (PMID 37365581, 2023). "The demethylase alkB homologue 5 (ALKBH5) plays diverse roles in different cancers, but its role during gastric cancer (GC) progression is not well known." (PMID 36864711, 2023). "As a demethylase, ALKBH5 has been reported to have oncogenic roles in the progression of lung cancer, osteosarcoma, gastric cancer, colon cancer, and ovarian cancer." (PMID 36376862, 2022). "The detection of mRNA levels of m6A-modified enzymes (METTL3, WTAP, METTL14, VIRMA, RBM15, FTO, and ALKBH5) in gastric cancer tissues and adjacent tissues showed that the mRNA level of METTL3 was significantly higher in gastric cancer tissues." (PMID 34394353, 2021). "ALKBH5 stimulates gastric cancer’s invasion and metastasis through lowering lncRNA NEAT1’s methylation." (PMID 34476213, 2021). "ALKBH5 depends on its m6A demethylation ability to facilitate gastric cancer metastasis and osteosarcoma cell proliferation." (PMID 34853296, 2021). "A previous report suggested that ALKBH5 overexpression promotes invasion and metastasis in gastric cancer cells." (PMID 32323721, 2020). "In gastric cancer 15, using 3 m6A RNA methylation regulators (FTO, RBM15, ALKBH5), a prognostic risk signature was established." (PMID 33033522, 2020). "ALKBH5 favors the invasion and metastasis of gastric cancer (GC) by demethylating lncRNA nuclear paraspeckle assembly transcript 1 (NEAT1)." (PMID 32767982, 2020). "For instance, the upregulation of the lncRNA NEAT1 in gastric cancer was attributed to a decrease in methylation by the RNA demethylase ALKBH5 (alkylation repair homolog protein 5)." (PMID 33291485, 2020). "Based on this finding, we derived a risk signature, using 3 m6A RNA methylation regulators (FTO, RBM15, ALKBH5), that is not only an independent prognostic marker but can also predict the clinicopathological features of gastric cancer." (PMID 31681576, 2019). "Similarly, NAD+ levels and the NAD+/NADH ratio were significantly decreased under hypoxia following demethylases knockdown, suggesting that FTO and ALKBH5 are key regulators of energy homeostasis in gastric cancer cells." (PMID 39824841, 2025). "In contrast, a series of studies implicated ALKBH5 as a tumor suppressor in diverse caners, including non-small-cell lung cancer, esophageal cancer, pancreatic cancer, gastric cancer, and so on." (PMID 40001461, 2025). "Additionally, ALKBH5 attenuates gastric cancer tumorigenesis and metastatic progression by repressing the translation of uncapped WRAP/53 RNA isoforms through translational regulatory mechanisms." (PMID 40986143, 2025). "For example, a decreased expression of ALKBH5 was detected in GC samples, and ALKBH5 expression was correlated with clinical tumor distal metastasis and lymph node metastasis, while the demethylase ALKBH5 suppressed cell invasion of gastric cancer via the PKMYT1 m6A modification." (PMID 38745044, 2024). "ALKBH5 is an oncogene that accelerates gastric cancer proliferation, metastasis, and invasion." (PMID 39136000, 2024).
gastric cancer (continued). "Among m6A demethylases, ALKBH5 affects gastric cancer development by demethylating lncRNAs." (PMID 38351139, 2024). "ALKBH5 (alkylation repair homolog 5) promotes invasive spread of gastric cancer by lowering the methylation of lncRNA NEAT1, and it may be a possible target for therapy." (PMID 38329551, 2024). "Furthermore, we confirmed that gastric cancer patients with elevated ALKBH5 expression had poorer OS among our patients (n = 117, p < 0.01, log-rank test)." (PMID 38007439, 2023). "To ascertain whether CHAC1 plays a predominant role in ALKBH5-mediated gastric cancer proliferation, we generated two mouse models overexpressing these genes." (PMID 38007439, 2023). "As same in gastric cancer, ALKBH5 also could up-regulate LncRNA NEAT1 expression by inhibiting m6A enrichment on LncRNA NEAT1 in hepatocellular carcinoma and in colon cancer." (PMID 37365581, 2023). "However, recent studies also reported the inhibitory role of ALKBH5 in many cancers, such as gastric cancer, and osteosarcoma." (PMID 37858219, 2023). "Other studies showed that ALKBH5 could promote the metastasis and invasion of gastric cancer by demethylating the expression of lncRNA NEAT1 and that METTL14 acts as a prognostic biomarker in colorectal cancer by downregulating oncogenic lncRNA XIST." (PMID 35309906, 2022). "In gastric cancer, a risk signature was constructed using 3 m6A RNA methylation regulators (FTO, RBM15, and ALKBH5), which not only was an independent prognostic marker but could also predict the clinicopathological features of gastric cancer." (PMID 33628782, 2021). "Also, the mRNA level of ALKBH5 was higher in gastric cancer tissues than in adjacent tissues, while the mRNA level of FTO was lower in gastric cancer tissues than in adjacent tissues." (PMID 34394353, 2021). "Similarly, an oncogenic role has been suggested for ALKBH5, as its knockdown inhibited lung tumorigenesis and gastric cancer invasion and metastasis." (PMID 34683137, 2021). "Besides, ALKBH5 participated in the carcinogenicity of gastric cancer by affecting the methylation of NEAT1." (PMID 32742194, 2020). "Moreover, compare with low risk group patients, gastric cancer patients generally contain a higher proportion of FTO, lower proportion of ALKBH5 and RBM15 in the high risk group." (PMID 31681576, 2019). "M6A “eraser” related gene including FTO and ALKBH5 were found to be a reliable prognostic and predictive tool in a recent study of 738 gastric cancer (GC) samples obtained from two independent datasets." (PMID 39009956, 2024). "In addition, the ALKBH5 silencing disrupts gastric cancer tumorigenesis via the JAK1 axis." (PMID 39136000, 2024). "A study found that circFOXP1 was highly expressed in gastric cancer (GC) and demonstrated that ALKBH5-mediated m6A modification of circFOXP1 promoted GC progression by regulating SOX4 expression and sponging miR-338-3p." (PMID 38745044, 2024). "However, ALKBH5’s function in gastric cancer (GC) has remained controversial." (PMID 38007439, 2023). "To evaluate if ALKBH5 suppressed CHAC1 expression steadily in GC, we re-examined the total mRNA expression of CHAC1 after ALKBH5 knockdown in several gastric cancer cell lines." (PMID 38007439, 2023). "Correlation between alkB homologue 5 (ALKBH5) expression and clinicopathological characteristics of gastric cancer (GC)." (PMID 36864711, 2023). "In our study, we present additional evidence through the integration of RNA-seq and MeRIP-seq data, identifying CHAC1 as a potential downstream target of ALKBH5 in gastric cancer (GC)." (PMID 38007439, 2023). "Thirdly, we hypothesize that FTO and ALKBH5 serve as “m6A erasers” to regulate gastric cancer." (PMID 33718213, 2021). "The m6A RNA modifications and their regulators—including METTL3, ALKBH5, FTO, YTHDFs, hnRNPA2B1, and IGF2BP2—have particularly emerged as key drivers of chemotherapy resistance in gastric cancer." (PMID 41228380, 2025).
gastric cancer (continued). "We further apply pum6a to study the dynamic regulation of m6A demethylases in gastric cancer under hypoxia, revealing distinct roles for FTO and ALKBH5 in modulating m6A modifications and uncovering key insights into m6A -mediated transcript stability." (PMID 39824841, 2025). "In this way, ALKBH5 directly downregulates CHAC1 and contributes to ferroptosis resistance in gastric cancer cells." (PMID 41488051, 2025). "ALKBH5-mediated CHAC1 downregulation enhances GSH levels and strengthens antioxidant capacity, resulting in the increased proliferation of gastric cancer cells." (PMID 40227215, 2025). "Conversely, ALKBH2, ALKBH3, ALKBH5, ALKBH6, and ALKBH7 showed low expression in gastric cancer tissues." (PMID 38902235, 2024). "Silencing ALKBH5 or LINC00659 disrupted the JAK1 axis, inhibiting gastric cancer tumorigenesis and progression." (PMID 39192357, 2024). "Mechanistically, ALKBH5 downregulates CHAC1 expression by eliminating m6A modification, disrupting ROS homeostasis in gastric cancer." (PMID 38007439, 2023). "Therefore, ALKBH5 may be a potential predictor and therapeutic target for gastric cancer." (PMID 38007439, 2023). "Inhibiting ALKBH5 upregulates the m6A levels of glutaminase 2 (GLS2) and inhibits the malignant biological behavior of gastric cancer cells." (PMID 37325047, 2023). "Through our study, we found that TRA2A, METTL3, ALKBH5 and TYHDC2 were significantly down-regulated in gastric cancers cells." (PMID 36003776, 2022). "Both ALKBH5 and the lncRNA nuclear paraspeckle assembly transcript 1 (NEAT1) were highly expressed in gastric cancer cells and gastric cancer tissues." (PMID 35628623, 2022). "ALKBH5 decreased the level of lncRNA nuclear paraspeckle assembly transcript 1 (NEAT1), which was overexpressed in gastric cancer cells and tissue, and took a great part in the invasion and metastasis of gastric cancer." (PMID 32742194, 2020). "ALKBH5, through m6A and NEA-T1, affects the expression of the polyclonal inhibitor complex subunit E2H2, thereby promoting the invasion and metastasis of gastric cancer cells." (PMID 33552994, 2020). "In contrast, high expression of ALKBH5 (HR = 0.94, 95% CI = 0.89–0.98) and RBM15 (HR = 0.83, 95% CI = 0.74–0.93), have a better survival in patients with gastric cancer." (PMID 31681576, 2019). "Demethylases such as ALKBH5 and FTO also reshape cytokine networks in gastric cancer." (PMID 41228380, 2025). "ALKBH5, as an m6A eraser, could inhibit the methylation of lncRNA NEAT1 and further facilitate metastasis and invasion of gastric cancer." (PMID 40069867, 2025). "ALKBH5 also removes the m6A modification of JAK1 mRNA, leading to upregulation of JAK1 expression mediated by LINC00659 in an m6A-YTHDF2-dependent manner, consequently activating the JAK1/STAT3 pathway in gastric cancer." (PMID 39136000, 2024). "We found that ALKBH5 expression and the levels of K235 acetylation of ALKBH5 and its acetyltransferase KAT8 are increased and its deacetylase HADC7 level is downregulated in liver and gastric cancers." (PMID 37369679, 2023). "Previous studies reported that elevated m6A levels of peripheral blood in patients with gastric cancer might be due to downregulation of FTO and ALKBH5, which belonged to “erasers”." (PMID 34659267, 2021). "ALKBH5 combines with lncRNA-NEAT1 to remove the m6A modification that occurs on it and then affects the expression of the polyclonal inhibition complex subunit, EZH2, which in turn affects the invasion and metastasis of gastric cancer cells." (PMID 33552994, 2020). "In gastric cancer (GC), histone acetylation upregulated HSPA4, which enhanced ALKBH5 protein stability." (PMID 41562066, 2025). "Additionally, the study found that the expressions of two m6A demethylases, ALKBH5 and FTO, were substantially suppressed in both in vitro and in vivo samples, suggesting a possible correlation between elevated m6A levels and the development of gastric cancer." (PMID 39009956, 2024).
gastric cancer (continued). "LINC00958 promotes aerobic glycolysis of GC cells by enhancing the stability of GLUT1 mRNA; ALKBH5 promotes the high expression of lncRNA NEAT1 in gastric cancer cells and tissues through demethylation." (PMID 35070987, 2021). "A mechanistic study showed that ALKBH5-mediated m6A modification of circFOXP1 promoted gastric cancer progression by regulating SOX4 expression and sponging miR-338-3p, resulting in a promoting effect on GC progression." (PMID 38745044, 2024).